MIR202 (microRNA 202)
Synonyms: hsa-mir-202; MIRN202; mir-202
Gene: MicroRNA gene on chromosome 10 (133,247,511 to 133,247,620, reverse strand). Ensembl gene ENSG00000284219.
Gene Ontology:
Cellular component: RISC complex
Diseases named in the same sentence as MIR202 in open-access papers:
MIR202 is named in the same sentence as 1 disease in open-access papers, as found by Europe PMC text mining. Sharing a sentence is not in itself a finding about the gene and the disease. The quoted sentences say what the papers report.
gastric cancer (1 paper, 2023). A primary or metastatic malignant neoplasm involving the stomach. "In this study, mGWAS-based studies localized four non-coding RNAs associated with gastric cancer prognosis, namely, MIR202HG (MIR202 host gene), MIR378D1, LINC02472, and LINC02310." (PMID 37894938, 2023).